SLFN12 (schlafen family member 12)
Diseases named in the same sentence as SLFN12 in open-access papers (continued):
Sharing a sentence is not in itself a finding about the gene and the disease.
prostate carcinoma (3 papers, 2020 to 2024). A carcinoma that arises from epithelial cells of the prostate gland. "Although this SLFN12 study did not conduct survival analysis in prostate cancer, better differentiation of cancer cells is known to have a better outcome; therefore, SLFN12 expression is predicted to correlate with better prostate cancer outcomes." (PMID 34571887, 2021). "Unlike the nuclear-localized SLFN5 and SLFN11, the intermediate family SLFN12, which lacks nuclear import signal and localizes to the cytoplasm, also has a differentiation effect in prostate cancer cells." (PMID 34571887, 2021). "Overexpressing SLFN12 in prostate cancer LNCaP and PC-3 cells induces the differentiation of these cells as indicated by the reduced PSA expression and increased dipeptidyl-peptidase-4 and E-cadherin expression independently of the other known differentiation pathways." (PMID 34571887, 2021).
allergic rhinitis (2 papers, 2023 to 2024). Inflammation of the nasal mucous membranes caused by an IgE-mediated response to external allergens. "In another study, researchers observed an increase in SLFN12 gene methylation levels in the peripheral blood of patients with allergic rhinitis, with methylation levels correlating positively with inflammation severity, suggesting SLFN12’s association with immune response and inflammation." (PMID 38075038, 2023).
autoimmune disease (2 papers, 2023 to 2024). A disorder resulting from loss of function or tissue destruction of an organ or multiple organs, arising from humoral or cellular immune responses of the individual to their own tissue constituents. "Furthermore, SLFN12 seems to be linked with autoimmune diseases such as MS." (PMID 38832156, 2024). "Fortunately, numerous studies have explored the relationship between SLFN12 methylation and autoimmune diseases and inflammatory responses." (PMID 38075038, 2023). "However, a specific process through which SLFN12 may contribute to the development of autoimmune diseases remains in question and needs further research." (PMID 38832156, 2024).
colon cancer (2 papers, 2021 to 2024). "Although Slfn3 is not expressed in humans, such findings might predict the role of human orthologs of Slfn3 (SLFN12) in colon cancers and further support the need to explore the potential role of SLFN12 in colon cancer." (PMID 34571887, 2021).
lung carcinoma (2 papers, 2020 to 2021). "Although c-myc knockdown reported to induce apoptosis in lung cancer cells, it still needs to be determined if SLFN12 induces apoptosis through c-myc pathway or another independent pathway." (PMID 32987632, 2020). "Although the KM plotter data and the Cancer Genome Atlas data are not completely independent, we used both to study the effects of SLFN12 on human lung cancer biology." (PMID 32987632, 2020). "Genomic analysis of human lung cancers suggested that SLFN12 expression inversely correlated with c-myc gene signature in LUAD, but not in LUSC, and we validated this finding at the protein level using cell lines." (PMID 32987632, 2020). "Our analysis identified SLFN12 as a favorable prognostic factor in lung cancer, but more importantly, stratified this survival correlation by histological subtype." (PMID 32987632, 2020). "Gene expression analysis of two human lung cancer datasets revealed correlations of SLFN12 with different gene signatures." (PMID 32987632, 2020). "Our results indicate that SLFN12 does play a role in lung cancer biology." (PMID 32987632, 2020). "We now want to understand whether SLFN12 plays a major role in lung cancer biology and prognosis and whether this role might differ between adenocarcinoma and squamous carcinoma of the lung." (PMID 32987632, 2020). "SLFN12 also sensitizes cancer cells, including lung cancer, to PDE3A inhibitors." (PMID 32987632, 2020). "However, even in the absence of a specific drug to target tumors on the basis of their SLFN12 levels, the ability to separate lung cancer patients into high versus low SLFN12 expression may help in predicting the prognosis and subsequent aggressiveness of the chemotherapy." (PMID 32987632, 2020). "However, a recently patented specific PDE3A inhibitor compound has been identified (DNMDP) that appears to induce apoptosis in a set of NCI-60 cancer cells, including lung cancer cells, by enhancing the interaction of PDE3A with SLFN12." (PMID 32987632, 2020). "Taking together the differential survival effect of SLFN12 in LUAD, but not in LUSC in two other databases, these results suggest that the role of SLFN12 in lung cancer may be specific to the histological subtype and not uniform across all lung cancers." (PMID 32987632, 2020).
acute myeloid leukemia (1 paper, 2025). Acute myeloid leukemia (AML) is a group of neoplasms arising from precursor cells committed to the myeloid cell-line differentiation. "We examined the role of SLFN12, a member of the Schlafen (SLFN) family of interferon-regulated genes and proteins in leukemogenesis, and its potential as a therapeutic target in acute myeloid leukemia (AML)." (PMID 41150877, 2025).
cervical adenocarcinoma (1 paper, 2021). An adenocarcinoma arising from the cervical epithelium. "DNMDP-derived molecule (R)-30/BRD9500 induces PDE3A/SLFN12 interaction in cervical adenocarcinoma HeLa cells to promote apoptosis." (PMID 34571887, 2021). "Interestingly, SLFN12 induces apoptosis in Hela cells (cervical adenocarcinoma) in response to 17-ß-estradiol (E2) treatment." (PMID 34571887, 2021).
gastric cancer (1 paper, 2024). A primary or metastatic malignant neoplasm involving the stomach. "Previous studies have implicated that SLFN12 is involved in immune infiltration in gastric cancer." (PMID 39740094, 2024).
leukemia (1 paper, 2025). A malignant (clonal) hematologic disorder, involving hematopoietic stem cells and characterized by the presence of primitive or atypical myeloid or lymphoid cells in the bone marrow and the blood. "Our study reveals stabilization of SLFN12 protein as early as 4 hours after treatment at very low concentrations of BAY 2666605 in leukemia cells both in vitro and in vivo, resulting in potent antileukemic responses and forming the basis for future clinical–translational efforts in that direction." (PMID 41150877, 2025). "We also examined protein expression of SLFN12, PDE3A, and PDE3B in a panel of leukemia cell lines and found that HEL cells exhibit readily detectable amounts of all three proteins." (PMID 41150877, 2025). "Besides HEL, SLFN12 was also readily detectable in U937 and SET-2 cells, and to a lesser extent in the remaining leukemia lines, whereas PDE3A was below detection levels in K-562, KG-1, U937, OCI-AML-5, and MV-4-11 cells." (PMID 41150877, 2025).
lung squamous cell carcinoma (1 paper, 2020). "In particular, in each dataset, the correlation between SLFN12 and the myc-associated gene signature differed between the adenocarcinoma and squamous cell lung cancer subtypes." (PMID 32987632, 2020). "Although we focused here on adenocarcinoma and squamous cell carcinoma of the lung, it would be interesting to examine the effect of SLFN12 on large cell and small cell lung cancer survival, but the databases available to us did not contain sufficient sample size to perform such analyses." (PMID 32987632, 2020). "In contrast, SLFN12 expression did not correlate with survival in patients with lung squamous cell carcinoma subtype (hazard ratio = 1.03, n = 524, p-value = 0.78)." (PMID 32987632, 2020).
melanoma (1 paper, 2021). A malignant, usually aggressive tumor composed of atypical, neoplastic melanocytes. "Although SLFN11, SLFN12, SLFN13, and SLFN14 are expressed comparably in primary melanocytes and malignant melanoma cells, the high expression of SLFN5 in primary melanocytes is suppressed at both mRNA and protein levels in malignant melanoma cells." (PMID 34571887, 2021).
meningioma (1 paper, 2025). A generally slow growing tumor attached to the dura mater. "DEG analysis identified 250 and 68 significantly overexpressed genes in the VS and meningioma tumour samples respectively compared to their control tissues, including six significantly co-overexpressed genes: COL1A, ERBB2, SLFN12, SLIT2, PDGFD and CDH1." (PMID 41437121, 2025).
Obesity (1 paper, 2022). Accumulation of substantial excess body fat. "We also analyzed the expression of FBXW7, MBOAT2, STXBP4, SPARCL1, and UTS after SLFN12 overexpression because these are obesity-related genes." (PMID 36291149, 2022). "Further analysis was performed to determine whether SLFN12 may regulate specific genes involved with differentiation and restitution of intestinal mucosa and obesity-related genes from the significant 74 genes observed above." (PMID 36291149, 2022).
squamous cell carcinoma (1 paper, 2020). A carcinoma arising from squamous epithelial cells. "The question of how SLFN12 drives prognosis and why it is different in adenocarcinoma from squamous cell carcinoma awaits further exploration." (PMID 32987632, 2020).
cancer (22 papers, 2017 to 2025). A tumor composed of atypical neoplastic, often pleomorphic cells that invade other tissues. "Cancers frequently escape tumor suppressors, such as SLFN12, by developing downstream mutations that change the regulated expression of genes necessary for cancer cell immortality." (PMID 39594803, 2024). "It has been described that small molecule compounds, which stabilize complex formation between the phosphodiesterase PDE3A and SLFN12, cause selective cancer cell killing." (PMID 35037067, 2022). "SLFN12 causes differential expressions of significant cancer genes, but how they change in response to chemotherapy remains unknown." (PMID 39594803, 2024). "Because SLFN12 acts in many ways, and because cancers frequently develop downstream mutations to escape from potential tumor suppressors such as SLFN12, it may be important to investigate not just SLFN12 but its downstream and associated genes." (PMID 36672349, 2023). "In solid tumors, the protein–protein interaction between PDE3A and SLFN12 is well established in several cancer types, and the crystallized structure for this interaction has been resolved." (PMID 41150877, 2025). "The expression of SLFN12 was highest in AML compared with all other cancer types included in TCGA Pan-Cancer Atlas." (PMID 41150877, 2025). "The interaction of SLFN12 with the catalytic domain of PDE3A activates SLFN12, which cleaves tRNALeu and induces apoptosis and death of a large variety of cancer cells." (PMID 40497949, 2025). "In initial studies, we used TCGA Pan-Cancer Atlas to assess SLFN12 mRNA expression across several cancer types." (PMID 41150877, 2025). "DNMDP stabilizes the interaction between PDE3A and Schlafen 12 (SLFN12), inducing cytotoxicity in cancer cells with elevated expression of both proteins." (PMID 41179677, 2025). "SLFN11, SLFN5, SLFN13, and SLFN12 are broadly transcribed in cancer cells, while SLFN12L, SLFN14, and SLFNL1 display reduced levels of expression." (PMID 39558948, 2024). "In the future, exploration into mutations within the active site of SLFN12 would be interesting to see if a similar effect occurs on SLFN family expressions and changes in SLFN12 signature cancer genes." (PMID 39594803, 2024). "SLFN12 influences the expressions of important cancer genes and other SLFN family members, but it is unclear how these genes change following chemotherapy." (PMID 39594803, 2024). "This study indicates that SLFN12 overexpressing TNBC cells with chemotherapy agents resulted in the differential expressions of eight cancer genes." (PMID 39594803, 2024). "Treating SLFN12-overexpressing TNBC cells with chemotherapy agents resulted in the differential expressions of eight cancer-related genes." (PMID 39594803, 2024). "SLFN11, SLFN5, SLFN13, and SLFN12 exhibit a wide range of transcription levels in cancer cells, whereas SLFN12L, SLFN14 and SLFNL1 are barely expressed in cancer cell lines." (PMID 35768579, 2022). "PDE3A binding increases SLFN12 RNase activity, and SLFN12 RNase activity is required for DNMDP-mediated cancer cell killing." (PMID 34272366, 2021). "The small molecule DNMDP acts as a velcrin by inducing complex formation between phosphodiesterase PDE3A and SLFN12, which kills cancer cells that express sufficient levels of both proteins." (PMID 34272366, 2021). "DNMDP promotes phosphodiesterase 3A (PDE3A) physical interaction with SLFN12 and induces apoptosis in 766 cancer cell lines, and depleting SLFN12 decreases the DNMDP sensitivity." (PMID 34571887, 2021). "DNMDP and related compounds, or velcrins, induce complex formation between the phosphodiesterase PDE3A and the SLFN12 protein, leading to a cytotoxic response in cancer cells that express elevated levels of both proteins." (PMID 34272366, 2021).
cancer (continued). "Data mining also indicated that co-occurrence of PDE3A and SLFN12 is rare in normal tissues, while their co-occurrence was found in a subset of cancer cell lines, opening the perspective of a novel class of cancer-selective cytotoxic compounds." (PMID 28454120, 2017). "DNMDP appeared to promote a neomorphic cytotoxic interaction between PDE3A and SLFN12, paving the way for a novel class of potential cancer therapeutic agents." (PMID 28454120, 2017). "Yet, evidence now shows that epigenetic silencing via DNA methylation, deacetylation, and post-translational phosphorylation can downregulate key members like SLFN11 and SLFN12, driving chemoresistance and poor outcomes in cancers such as gastric, colorectal, and ovarian tumors." (PMID 41303540, 2025). "PDE3A binding to SLFN12 results in cell killing and optimizing cancer therapeutics." (PMID 36046788, 2022). "Taken together, these results support the hypothesis that SLFN12 encodes an RNase, that SLFN12 RNase activity is stimulated by DNMDP-induced complex formation with PDE3A, and that SLFN12 RNase activity is required for DNMDP-induced cancer cell death." (PMID 34272366, 2021). "We speculate that SLFN12 may have a similar physiological function that is leveraged by velcrins to kill cancer cells expressing elevated levels of PDE3A and SLFN12." (PMID 34272366, 2021). "DNMDP worked only in cancer cells that exhibit high expression of SLFN12." (PMID 32987632, 2020). "Second, and conversely, basal SLFN12 levels in these cancer cells are already quite low." (PMID 32987632, 2020). "SLFN12 and its downstream signals might offer another potential pathway to target c-myc in cancer by regulating its expression." (PMID 32987632, 2020). "Interestingly, existing literature suggests that hypermethylation-mediated silencing of SLFN11 and SLFN12 disrupts DNA damage recognition, impairs apoptosis, and promotes chemoresistance across multiple cancers, allowing malignant cells to persist despite therapeutic intervention." (PMID 41303540, 2025). "In fact, velcrin-based SLFN12 modulation has shown significant potential for treating certain SLFN12- and PDE3A-positive cancers." (PMID 41150877, 2025). "Velcrins were found to have potent anticancer activity and selectively kill cancer cells with elevated PDE3A and SLFN12 expression." (PMID 39166256, 2024). "Until now, the targeting of SLFN12 through the use of velcrins has shown great potential for the treatment of SLFN12- and PDE3A-positive cancers." (PMID 38791884, 2024). "Two cancer progression pathways, the NAD signaling pathway and the superpathway of cholesterol biosynthesis, were downregulated with SLFN12 overexpression." (PMID 36672349, 2023). "For instance, SLFN12 reduces TNBC cell line proliferation and invasiveness while promoting differentiation and reducing the proportion of the cancer stem-cell-like subpopulation." (PMID 36672349, 2023). "The findings revealed that SLFN5, SLFN11, SLFN12, SLFN12L, SLFN13, and SLFN14 were expressed at higher levels in many cancers, including GC (stomach adenocarcinoma; STAD), while the SLFN14 expression levels were relatively low in all tumor and normal tissues." (PMID 36090985, 2022). "High SLFN12 expressing cancer cells are more sensitive to PDE3 inhibitors (zardaverine and quazinone) than low SLFN12 expresser cells." (PMID 34571887, 2021). "Cancer cells expressing elevated levels of both PDE3A and SLFN12 are typically sensitive to killing by DNMDP and other PDE3A-SLFN12 complex inducers." (PMID 34272366, 2021). "For example, the drug Anagrelide (ANA) can only inhibits cancer cell growth when both PED3A and SLFN12 are expressed." (PMID 34040636, 2021). "Velcrins, a class of small molecules that act like molecular glues by inducing a heterotetrameric complex between SLFN12 and the protein phosphodiesterase 3A (PDE3A), can promote cancer cell death by stabilizing SLFN12 protein, thereby enhancing its RNase activity." (PMID 41150877, 2025).
cancer (continued). "We did not explore SLFN11 and SLFN13 involvement in TNBC cell viability since it appeared that their expressions were controlled by SLFN12; however, that does not take away from their roles as investigated by others in cancer biology." (PMID 39594803, 2024). "In in vitro experiments, SLFN12 cleaves rRNA as an active RNase complex with phosphodiesterase 3A (PDE3A), enhancing DNMDP (6-(4-(diethylamino)-3-nitrophenyl)-5-methyl-4,5-dihydropyridazin-3(2H)-one)-induced cancer cell death." (PMID 35768579, 2022). "Here we demonstrate that SLFN12 is also an RNase, that this RNase activity is increased by incubation with velcrin-bound PDE3A, and that SLFN12 RNase activity is essential for velcrin-induced cancer cell killing." (PMID 34272366, 2021). "Currently, there is no proven therapeutic drug that specifically targets SLFN12 expression, as until our current studies, there has been no particular thought that SLFN12 was important in cancer." (PMID 32987632, 2020). "Similarly, SLFN12 activity is regulated by phosphorylation, with dephosphorylation at S368 and S573, triggered through interaction with PDE3A, activating its RNase function and promoting cancer-selective cytotoxicity." (PMID 41303540, 2025).